TTC39B (tetratricopeptide repeat domain 39B)
Description:
Regulates high density lipoprotein (HDL) cholesterol metabolism by promoting the ubiquitination and degradation of the oxysterols receptors LXR (NR1H2 and NR1H3).
Synonyms: C9orf52; FLJ33868
Tractability: PROTAC: ubiquitination databases record sites on it; its protein half-life has been measured.
Gene: Protein-coding gene on chromosome 9 (15,163,622 to 15,307,360, reverse strand). Ensembl gene ENSG00000155158.
Subcellular location (Human Protein Atlas): Endoplasmic reticulum
Gene Ontology:
Molecular function: protein binding
Biological process: cholesterol homeostasis; negative regulation of cholesterol storage; regulation of cholesterol efflux; regulation of cholesterol metabolic process
Genetic constraint (gnomAD): Loss-of-function variants: 51 observed, 55.87 expected, observed/expected ratio (o/e) 0.91, 90% interval 0.73 to 1.15. The upper end of that interval is the gene's LOEUF score, 1.15, which puts it in group 5 of 6, group 1 being the genes least tolerant of losing a copy. Missense variants: 728 observed, 623.2 expected, observed/expected ratio (o/e) 1.17, 90% interval 1.1 to 1.24. Synonymous variants: 282 observed, 241.56 expected, observed/expected ratio (o/e) 1.17, 90% interval 1.06 to 1.29.
Homologues: Orthologues: chimpanzee TTC39B (99% identical), macaque TTC39B (99% identical), rabbit TTC39B (91% identical), dog TTC39B (90% identical), guinea pig TTC39B (90% identical), rat Ttc39b (89% identical), mouse Ttc39b (88% identical), pig TTC39B (87% identical), tropical clawed frog ttc39b (64% identical), Caenorhabditis elegans ttc-39B (34% identical), zebrafish ttc39b (33% identical). Paralogues in human: TTC39A (48% identical), TTC39C (24% identical).
Diseases named in the same sentence as TTC39B in open-access papers:
TTC39B is named in the same sentence as 7 diseases in open-access papers, as found by Europe PMC text mining. Sharing a sentence is not in itself a finding about the gene and the disease. The quoted sentences say what the papers report.
atherosclerosis (2 papers, 2018 to 2020). A disease characterized by the build-up of fatty material and calcium deposition in the arterial wall resulting in partial or complete occlusion of the arterial lumen. "Thus, the study led us to hypothesize that EGCG attenuated high-fat-mediated atherosclerosis at least partially through modulation of TTC39B, an HDL gene discovered in human genome-wide association studies." (PMID 29593532, 2018). "TTC39B is a novel potential therapeutic target for treating both steatohepatitis and atherosclerosis." (PMID 29593532, 2018). "To further explore the molecular mechanisms by which EGCG exerted anti-atherosclerotic activity, we examined the effects of EGCG on hepatic TTC39B expression, which modulated lipid metabolism and reduced the process of atherosclerosis." (PMID 29593532, 2018). "Conversely, tetratricopeptide repeat (TPR) domain protein 39B (TTC39B, C9orf52) (T39), a high density lipoprotein (HDL) gene discovered in human genome wide association studies (GWAS) 44, 45, is associated with atherosclerosis and steatohepatitis as well as inflammation." (PMID 32913470, 2020). "TTC39B deficiency displayed increased HDL-cholesterol levels associated with increased enterocyte Abca1 expression, increased LXR protein, decreased fatty liver, decreased LDL levels, and reduced atherosclerosis." (PMID 29593532, 2018). "Therefore, reduction of TTC39B and enhancement of the LXRα-ABCA1/ABCG5/8 pathway was at least partly responsible for the inhibitory effect of EGCG on the anti-inflammatory and lipid-regulatory effects in high-fat-induced atherosclerosis." (PMID 29593532, 2018).
Allergy (1 paper, 2017). An allergy is an immune response or reaction to substances that are usually not harmful. "However, nonsynonymous mutations were identified in the coding sequences of Cer1, Ttc39b, Ccdc171, Cntln, Adamtsl1, Haus6, Gm12551, and Dennd4c, but these genes do not have any prior documented associations with allergy, IgE, or asthma." (PMID 28696925, 2017).
dyslipidemia (1 paper, 2018). "In the present study, we uncovered a novel mechanism by which EGCG, a major ingredient of green tea, attenuated atherosclerotic plaque formation by modulated system inflammation and dyslipidemia possibly in a TTC39B-dependent manner." (PMID 29593532, 2018).
lipid metabolism disorder (1 paper, 2018). "The major new finding of the present study was that EGCG, a major ingredient of green tea, modulated high-fat-mediated hepatic TTC39B expression, which were responsible for lipid metabolism disorder in ApoE-/- mice." (PMID 29593532, 2018).
Obesity (1 paper, 2022). Accumulation of substantial excess body fat. "Here, authors used multiple ASOs sequences to silence tetratricopeptide repeat protein 39B (TTC39B) in mice, resulting in protection against diet-induced obesity." (PMID 35295579, 2022).
tumour (1 paper, 2022). "Genes specifically lost in tumour samples with high NCS include KIAA1644, TAMM41, GRM7, TTC39B and FREM1." (PMID 35326573, 2022).
TTC39B also shares sentences with these, for which no sentence is quoted: asthma (1 paper).